IL17A (interleukin 17A)
Diseases named in the same sentence as IL17A in open-access papers (continued):
Sharing a sentence is not in itself a finding about the gene and the disease.
psoriasis (continued). "Psoriasis patients with moderate-to-severe disease have significantly elevated serum IL-17A levels, which appear to be associated with higher risk of developing cardiovascular complications including stroke and myocardial infarction." (PMID 27595115, 2016). "More recently, IL-17A blocking agents have been shown to have rapid and high efficacy in clinical trials, as described later, further emphasising the pathogenic role of IL-17A signalling in psoriasis." (PMID 26573299, 2016). "The new generation of antipsoriatic biologics directly targeting IL-23 or IL-17A underlines the central role of these cytokines in psoriasis pathogenesis." (PMID 27158469, 2016). "IL-2 and IL-17A have been reported to be responsible for activating pathogenic inflammation in a number of inflammatory skin diseases such as psoriasis." (PMID 25705127, 2015). "Investigators have confirmed that IMQ-induced skin inflammation is associated with the IL-23/IL-17A axis and can serve as a model for analyzing the pathogenic mechanisms associated with psoriasis-like dermatitis." (PMID 25165479, 2014). "The IL23/Th17 pathway and especially cytokine IL-17A is a key cytokine that activates pathogenic inflammation in psoriasis." (PMID 25153527, 2014). "IL-17A signatures from disparate studies were repeatedly associated with psoriasis DEGs, particularly the PP-increased DEGs." (PMID 23915137, 2013). "It is known that IFN-γ and IL-17A are associated with psoriasis and a synergistic activation of hBD-2 by these two cytokines has been reported." (PMID 23555696, 2013). "The cytokine interleukin 17A, which amongst other cell types is produced by T cells, has strong pro-inflammatory potential and has been clearly associated with psoriasis, and it also contributes to the pathology of atopic dermatitis." (PMID 23094018, 2012). "Specifically, human Vγ9Vδ2+ cells, which are induced to express IL-17A in the presence of IL-1β, have been implicated as playing a prominent role in psoriasis." (PMID 22891068, 2012). "The cytokine IL-17A is pathogenic in inflammatory and autoimmune diseases such as multiple sclerosis, psoriasis, inflammatory bowel disease, systemic lupus erythematosus, and rheumatoid arthritis." (PMID 21062492, 2010). "This response is magnified by priming with psoriasis-associated cytokines, IL-17A and IFNγ." (PMID 40121229, 2025). "Additionally, serum IL-13 levels and IL-13-related cytokine ratios (e.g., IFN-γ/IL-13, IL-17A/IL-13) have been associated with clinical responses to biologic therapies in psoriasis." (PMID 40650209, 2025). "However, dysregulated IL-17A expression is strongly linked to several human diseases, such as multiple sclerosis (MS), psoriasis, systemic lupus erythematosus (SLE), rheumatoid arthritis (RA), and asthma." (PMID 40821838, 2025). "IL-17A is a pro-inflammatory cytokine that plays a role in the recruitment and activation of immune cells, and it is associated with inflammatory conditions such as psoriasis." (PMID 39839224, 2025). "Additional studies have indicated that IL-9 also plays a crucial role in guttate psoriasis by upregulating IL-17A through its impact on cutaneous lymphocyte-associated antigen (CLA)+ T cell viability, thereby promoting inflammatory responses in guttate psoriasis." (PMID 40303401, 2025). "Compared with monoculture, psoriasis-derived mesenchymal stromal cells (PsO-MSCs) co-cultured with healthy donor MSCs (H-MSCs) secreted substantially lower levels of hallmark psoriatic pro-inflammatory cytokines (IL-6, IL-12, IL-13, IL-17A, TNF, and G-CSF)." (PMID 41226338, 2025). "IL-17A has been implicated in the pathogenesis of inflammatory diseases, such as psoriasis and AD." (PMID 40355181, 2025). "The suppression of type 17-associated cytokines, particularly IL-17A and IL-23A, through necroptosis inhibition suggests that necroptosis may contribute to psoriasis pathogenesis via type 17 inflammation." (PMID 40332377, 2025).
psoriasis (continued). "Specifically, HLA-Cw6, the primary psoriasis genetic susceptibility allele and five variants in the protein-coding and untranslated regions of the IL-17A gene have been tested for association with response to Secukinumab and Ixekinumab, with no positive results." (PMID 41153404, 2025). "WY14643 treatment significantly downregulated psoriasis‐associated inflammatory cytokines and chemokines (Il17a, Il1b, Cxcl1, Cxcl2, Cxcl3, Cxcl15, and Csf3) as well as the antimicrobial peptides S100a8 and S100a9 in IMQ‐induced skin lesions at the transcriptional level." (PMID 40878384, 2025). "In addition, IL-17A not only plays an important role in psoriasis but is also associated with hepatic diseases such as hepatocellular carcinoma and non-alcoholic fatty liver disease." (PMID 40861231, 2025). "In psoriasis, skin lesions arise from complex processes involving maladaptive immune signalling among keratinocytes, dendritic cells, neutrophils and T-cells; implicated pathways include IL-17A, IL-22, IL-23 and TNF-α signalling." (PMID 39959848, 2025). "Treatment with the psoriasis-associated cytokine, IL-17A, enhances IL-36γ protein expression." (PMID 40121229, 2025). "This pathway bridges IL-17A-driven inflammation to epidermal hyperplasia, a hallmark of psoriasis." (PMID 40365308, 2025). "Finally, we confirmed that miR-26a-5p triggered cascade downregulation of biomarkers from the IL-23/IL-17A axis associated with psoriasis development while suppressing CDC6 and CCNE1 expression." (PMID 38446584, 2024). "A recent study on treatment response to the IL-17 A antibody Secukinumab in psoriasis patients demonstrated that ERAP2 deficient patients (as indicated by carrying the rs2248374 G/G genotype) had a 6-fold increased risk of treatment failure compared to ERAP2 proficient patients." (PMID 39123229, 2024). "Abnormally raised SFAs in the samples of psoriasis patients could activate dendritic cells and promote the proliferation of Th17 cells which produce the critical pathogenic factor IL-17A." (PMID 38185620, 2024). "The mouse model K14-IL-17Aind/+ overexpressing IL-17A in keratinocytes developed a severe form of psoriasis-like inflammation that was associated with increased CD11b+ proinflammatory myeloid cells in the circulation and with increased reactive oxygen species as well as endothelial dysfunction." (PMID 37953417, 2024). "Moreover, IL-33 lets DC mature, which enables the induction of differentiation into Th17 cells, producing IL-17A, strongly involved in the pathogenesis of psoriasis, by stimulating keratinocytes into proliferation and causing epidermal thickening." (PMID 38666958, 2024). "Specific research suggests that the higher risk of cardiovascular disease in individuals with psoriasis may be due to the burden of inflammatory disease, which IL-17A influences." (PMID 39104857, 2024). "The IL-17A gene single-nucleotide polymorphism and fungal growth are associated with psoriasis." (PMID 39200988, 2024). "This could be a promising alternative treatment for IL-17A-driven psoriasis and associated comorbidities." (PMID 38892253, 2024). "Interestingly, deficiency of AIM2 reduced the development of IMQ-induced psoriasis by decreasing the production of type 3 cytokines (such as IL-17A and IL-23) and infiltrating immune cells into the inflammatory site." (PMID 39352743, 2024). "Encouragingly, the IL‐17A inhibitor treatment was demonstrated to be associated with a significant improvement in skin clearance and amelioration of depression symptoms in most patients with psoriasis." (PMID 39660880, 2024). "We then took advantage of the IMQ-induced psoriasis–like model and determined whether the loss of IL-17A signaling in IL-17RA–deficient mice (IL17ra–/–) would affect AIM2 expression in the skin." (PMID 39352743, 2024). "Moreover, TNF-α acts with IL-17A, co-regulating cytokines and keratinocyte genes associated with psoriasis and influencing keratinocyte function." (PMID 39311381, 2024).
psoriasis (continued). "Notably, there are reports of paradoxical BP reactions associated with IL-17A inhibitors used for other conditions, such as psoriasis." (PMID 39451595, 2024). "During IMQ-induced skin inflammation, the expression of AIM2 inflammasome components, such as AIM2, ASC, and pro-caspase-1, in skin lesions is upregulated, and serum levels of IL-17A, a cytokine which has been implicated in the pathogenesis of psoriasis, are increased." (PMID 36982727, 2023). "In addition, DCs matured by IL-33 induce differentiation into Th17 cells, which produce large amounts of IL-17A; these in turn increase the proliferative capacity of keratinocytes and cause epidermal thickening in psoriasis." (PMID 37834081, 2023). "In psoriasis, uncontrolled keratinocyte proliferation is associated with activation of the mTOR pathway and involves different Th-1, Th-17, and Th-22 immune cells, and their effector cytokines (e.g., IL-1β, IL-6, IL-17A, TNF-α) that act on keratinocytes." (PMID 37371141, 2023). "In conclusion, we propose that inhibition of the IL-36 signaling pathway might constitute an attractive, alternative approach for treating IL-17A-driven psoriasis and psoriasis-linked comorbidities." (PMID 38162658, 2023). "In summary, impaired suppressive function of Tregs or an increased Th17/Treg ratio would cause psoriasis, mainly because these conditions can lead to an abnormal proinflammatory cytokine environment, such as upregulated IL-17A and IFN-γ and downregulated IL-10 and TGF-β." (PMID 36742336, 2023). "IL-17 and Th17 cells are strongly implicated in psoriasis, and the authors showed that inflammation led to enhanced IL-17A (the archetypal IL-17 member) expression in peripheral immune cells, with associated increases in NF-κB/p38 MAPK signalling and depressive-like behaviours." (PMID 37457896, 2023). "IL-17A is an inflammatory cytokine linked to psoriasis development and severity; using anti-IL-17 antibodies to block it is an effective existing treatment in psoriasis therapy." (PMID 37303600, 2023). "The expression of many genes known to be associated with psoriasis, including Lce3f, Sprr2b, Krt15, S100a8, S100a9, Il17a, Il17f, Il18, Il20, Il22, and Ccl20, was downregulated in the skin of IMQ-treated Camk4−/− mice compared with those of IMQ-treated Camk4+/+ mice." (PMID 35869084, 2022). "Psoriasis is a disease associated with sustained inflammation; therefore, we hypothesized that TC could reduce the IL-17A-induced skin inflammatory signaling pathway." (PMID 36498953, 2022). "Therefore, IκBζ has emerged as a key regulator of both IL‐17A and IL‐17F‐inducible psoriasis‐associated genes." (PMID 36245291, 2022). "Conversely, studies have suggested that anti-IL-17A treatment may reduce risk of CVD in patients with psoriasis albeit that adequately powered randomized trials with clinical endpoints are awaited." (PMID 35008981, 2022). "Interestingly, psoriasis patients who had been previously treated with IL-17A antagonists were associated with relatively mild or even asymptomatic COVID-19, suggesting a protective role of IL-17 inhibitors in ARDS." (PMID 35343786, 2022). "Its pathophysiology is multifactorial; the IL‐23/IL‐17A pathway is considered the central pathogenic axis and has been the target for many highly effective biologic drugs, which has been a major progress in the treatment of psoriasis patients." (PMID 36226669, 2022). "IL-17A was identified as another pathogenic cytokine in psoriasis." (PMID 35054813, 2022). "Second, Th17 cells and IL-17A are mainly pro-inflammatory, and they are considered to be associated with several autoimmune diseases, including psoriasis, ankylosing spondylitis (AS), rheumatoid arthritis (RA), systemic lupus erythematosus (SLE), and inflammatory bowel disease (IBD)." (PMID 35459141, 2022).
psoriasis (continued). "The relevance of HLA-Cw6 in psoriasis pathogenesis has also been confirmed by pharmacogenomic studies showing that its presence in patients associates with better response to the anti-IL-12/IL-23p40 ustekinumab or anti-IL-17A secukinumab drugs." (PMID 36423071, 2022). "One hallmark of psoriasis is the up-regulation of IL-17A in the skin." (PMID 35812457, 2022). "(2017) showed that the depression-like state caused by psoriasis in mice is accompanied by increased systemic/neuronal expression of IL-17A, which was associated with increased NFκB/p38MAPK signaling and inflammatory mediators in brain regions, and depression-like symptoms." (PMID 36189272, 2022). "Moreover, in psoriasis patients, it was shown that enhanced loss of Foxp3 is linked to Treg differentiation into IL-17A producing cells." (PMID 36450783, 2022). "Thus, the Th1 pathogenic paradigm of psoriasis began to shift towards a Th17-driven disease, considering IL-23 and IL-17A as critical Th17 upstream and downstream cytokines, respectively." (PMID 34201664, 2021). "We examined whether the key cytokines (TNFα, IL-22, IL-1β, IL-17A) implicated in the pathogenesis of psoriasis modulate the circadian oscillation of the clock genes in HaCaT keratinocytes." (PMID 35008548, 2021). "Nevertheless, this study on the lipid changed metabolites associated with IL-17A mAb treatment could provide a foundation for future in-depth research on the pathogenesis of psoriasis." (PMID 33602246, 2021). "IL-17A is the signature cytokine of Th17 cells and is often associated with various autoimmune and proinflammatory diseases, such as organ-specific inflammation and psoriasis." (PMID 34805416, 2021). "The stimulation with IL-17A + IL-36γ upregulated numerous psoriasis-associated genes." (PMID 34440590, 2021). "Currently, T cells and dendritic cells are considered as the primary immune cells that release cytokines associated with psoriasis, such as interleukin (IL)-17A, IL-22, tumor necrosis factor (TNF)-α, and interferon (IFN)-γ, which affect keratinocyte proliferation." (PMID 34955833, 2021). "In psoriasis, IL-17A-producing CD8+ TRM are regarded as one of the pathogenic populations in skin." (PMID 34501272, 2021). "However, excessive IL-17A production has been linked to autoimmune diseases such as psoriasis, psoriatic arthritis, rheumatoid arthritis and multiple sclerosis." (PMID 34752458, 2021). "In a very recent study, we demonstrated that the expression of interleukin-17A (IL-17A), a cytokine linked to many autoimmune diseases including rheumatoid arthritis, systemic lupus erythematosus, psoriasis, and multiple sclerosis, is increased in the skin of patients with severe CSU." (PMID 33801296, 2021). "Interestingly, psoriasis-associated cytokines especially IL-17A and IL-6, can directly positively regulate keratinocytes to over-express OAS2." (PMID 32849499, 2020). "IL-17A producing cells are thought to be pathogenic in driving inflammation in obesity and progression of obesity-related inflammatory diseases, suggesting that causality between psoriasis and adipogenesis is likely to be bidirectional." (PMID 32790787, 2020). "During psoriasis, keratinocytes attract T cells by releasing chemokines, while skin-infiltrating self-reactive T cells secrete proinflammatory cytokines, e.g., IFNγ and IL-17A, that cause epidermal hyperplasia." (PMID 31324882, 2020). "In addition, mRNA expression of the psoriasis-associated genes Il17a, Tnfa, S100a9, Il17c and Il1f9 was induced by tamoxifen in the ears and the back skin." (PMID 32597759, 2020). "This study provided the first evidence that topical Cal/BDP caused synergistic improvement of IMQ-induced psoriasis-like dermatitis in vivo while suppressing the expression of cytokines related to the IL-23/T17 pathogenic axis, such as IL-17a and IL-23a, in psoriatic lesions." (PMID 31705000, 2019).
psoriasis (continued). "Mechanistically, this psoriasis protection was mediated by IκBζ deficiency in keratinocytes abrogating the induction of specific proinflammatory target genes, including Cxcl5, Cxcl2, Csf2, and Csf3, in response to IL-17A or IL-36." (PMID 31622280, 2019). "In patients treated with anti-IL-17A monoclonal antibodies for psoriasis, routine serial repeat QFT-GIT testing was associated with lower seroconversion rate compared to real-world data of tumor necrosis factor-α inhibitors and anti-IL-12/23 antibody in Taiwan and in pivotal studies." (PMID 31881026, 2019). "However, variable relationships amongst the expression of psoriasis susceptibility genes and of IL17A, IL22, and IL23A were identified." (PMID 31019502, 2019). "Although the IL-23/Th17 pro-inflammatory axis is closely linked to development of psoriasis, psoriatic arthritis and rheumatoid arthritis, a substantial role for IL-17A/F cytokine and IL-17RA in intestinal inflammation such as inflammatory bowel disease and Crohn ́s disease has been documented." (PMID 30304852, 2018). "Direct evidence supporting the central role of IL-17A in psoriasis includes upregulation of IL-17A and related genes in lesional and non-lesional skin of patients with psoriasis and production of IL-17A by cells associated with psoriasis." (PMID 30109481, 2018). "ILC3s produce IL-17A and are implicated in psoriasis and PsA pathogenesis." (PMID 30109481, 2018). "With respect to CD8 T cell targetability, a recent study on a AGR mouse model of psoriasis has reported the accumulation of epidermal CD8+ T cells during psoriasis development which was associated with IL-17A production and increased keratinocyte proliferation." (PMID 29971067, 2018). "The involvement of IL-23 in psoriasis was supported by its ability to induce psoriasiform characteristics in a preclinical model of intradermal administration; a phenotype linked to the infiltration of IL-22- and IL-17A-producing T cells." (PMID 30127781, 2018). "Nevertheless, the role of IL-17A in psoriasis-associated atherosclerosis is still controversial." (PMID 29971067, 2018). "IL-9 has been associated with increased IL-17A production in an animal model of psoriasis." (PMID 30013558, 2018). "Moreover, transcription factor Sox13 is required for the maturation of IL-17A+Vγ4 T cells in the neonatal thymus, and its mutation is able to protect mice from psoriasis-like dermatitis." (PMID 29915573, 2018). "In addition to Th17 cells, Tc17 and γδ T-cells are a major source of IL-17A and these cells have been implicated in the pathogenesis of human psoriasis and various mouse skin inflammation models." (PMID 29155882, 2017). "IL-17A is a cytokine that is mainly produced by T helper 17 cells and plays a pathogenic role in systemic inflammatory diseases, such as multiple sclerosis, rheumatoid arthritis, psoriasis, etc.." (PMID 27827561, 2017). "Notably, blockade of IL17A in Crohn’s disease caused disease exacerbation, despite being well tolerated and therapeutically effective in psoriasis." (PMID 28782508, 2017). "Given that IL-17A is associated with a number of auto-immune diseases in humans, dissecting its molecular mechanism in keratinocytes will help in understanding its impact in psoriasis." (PMID 26781963, 2016). "In the CD4 compartment, we found that CCR6+ CD4+ TEM cells correlated with systemic inflammation measured as serum level of C-reactive protein (unpublished data), in line with the increase of IL-17A in serum of patients with severe psoriasis and with its association with cardiovascular diseases." (PMID 27595115, 2016). "In general, severe enteropathy develops in humans deficient in Foxp3 expression and mice deficient in Tregs, and Foxp3+ Tregs of psoriasis patients are susceptible to differentiation into IL-17A that has a highly pathogenic role in skin inflammation and the development of psoriatic plaques." (PMID 27802847, 2016).